SIRT1 (sirtuin 1)
Diseases named in the same sentence as SIRT1 in open-access papers (continued):
Sharing a sentence is not in itself a finding about the gene and the disease.
asthma (28 papers, 2017 to 2025). "Our in vivo findings demonstrate that myeloid-specific SIRT1 deletion exacerbates airway inflammation and remodeling associated with asthma." (PMID 36313381, 2022). "This study aimed to investigate the potential benefit and underlying mechanism of the SIRT1 agonist bergenin as a treatment for asthma." (PMID 36313381, 2022). "Here, we established a myeloid cell-specific SIRT1 conditional knockout (Sirt1fl/fl-LysMCre) mouse model of asthma using ovalbumin (OVA) induction and determined the underlying mechanism by which the SIRT1 agonist bergenin acts in the treatment of asthma." (PMID 36313381, 2022). "Here, using an experimental model of asthma, we sought to determine the underlying mechanisms of SIRT1 in the regulation of allergic airway inflammatory responses in macrophages using an experimental model of asthma." (PMID 34099590, 2021). "Our previous study has shown that serum SIRT1 levels in patients with asthma were positively associated serum IgE levels." (PMID 34099590, 2021). "For example, pterostilbene influences the AMPK/SIRT1 pathway to restrain oxidative stress and airway inflammation to ameliorate asthma." (PMID 39881825, 2025). "Serum levels of SIRT1 in asthma patients are positively correlated with IgE levels, while anti-SIRT1 autoantibodies are more abundant in inflammatory diseases such as ankylosing spondylitis." (PMID 38962006, 2024). "Recent studies have shown that individuals with asthma often have increased levels of pAMPK and SIRT1 and that AMPK/SIRT1/PGC1α plays a critical role in metabolic regulation and energy expenditure during the development of AAI." (PMID 39081309, 2024). "On the other hand, increased serum SIRT1 levels were noticed in acute ischemic stroke, asthma systemic lupus erythematosus and frailty." (PMID 38529393, 2024). "Concretely, hsa‐miR‐155‐5p was transported from AEC‐Exos to CD4+ T cells through SIRT1‐mediated pathway, which further induce the enhanced Th2 inflammation in acute asthma exacerbation after RSV infection." (PMID 38938285, 2024). "Specifically, the enhanced Th2 inflammation was induced by AEC‐Exos thorough transportation of hsa‐miR‐155‐5p–Sirtuin 1 (SIRT1) pathway during acute asthma exacerbation." (PMID 38938285, 2024). "The controversial role of SIRT1 in regulating asthma and other respiratory diseases can be attributed to the abundance of substrates and their great variability, in addition to the involvement of different regulatory pathways." (PMID 37987301, 2023). "More rigorous broad-scale studies are needed to determine the role of SIRT1 in the pathogenesis of asthma." (PMID 37987301, 2023). "SIRT1 is considered an auxiliary index for diagnosis and its activators represent novel therapeutic strategies for asthma." (PMID 37987301, 2023). "Some of these research papers studied the relationship between SIRT1 expression and asthma conditions." (PMID 37987301, 2023). "SIRT1 activation exerts an anti-inflammatory effect due to the inhibition of IL-6 and IL-8 and leads to improvements in the asthma inflammatory response." (PMID 37987301, 2023). "SIRT1 is expressed at low levels in the lungs of OVA‐induced asthmatic mice and the activation of SIRT1 can inhibit the onset of asthma." (PMID 36840485, 2023). "Consistent with animal data, Sirt1, Sirt3, and Sirt5 expression was decreased in the peripheral blood of patients with asthma compared to controls." (PMID 38135684, 2023). "On the other hand, other findings claimed that SIRT1 plays a pro-inflammation role and promotes airway inflammation in asthma." (PMID 37987301, 2023). "In the context of asthma, SIRT1 is thought to play an anti-inflammatory role by regulating Th2 cell differentiation and inhibiting pro-inflammatory pathways such as NFκB." (PMID 37047327, 2023). "For instance, experiments in animal model of asthma have shown that anthocyanins suppresses inflammatory responses in airways through decreasing activity of NF-κB pathway via the miR-138-5p/SIRT1 axis." (PMID 37441551, 2023).
asthma (continued). "Compared with other SIRTs, more research has been done on SIRT1 and the relationship between SIRT1 and asthma." (PMID 36117172, 2022). "It is worth mentioning that many studies have shown that SIRT1 is involved in virus-induced asthma exacerbations." (PMID 36117172, 2022). "We generated myeloid-specific SIRT1 conditional knockout (Sirt1fl/fl-LysMCre) mice and established an asthma model." (PMID 36313381, 2022). "Studies on animal models of asthma have shown that the expression of SIRT1 is downregulated in the lung tissues and upregulated in serum." (PMID 36117172, 2022). "Both gentiopicroside and pterostilbene have anti-inflammatory roles in asthma via upregulating the expression of SIRT1." (PMID 36117172, 2022). "To further elucidate the specific mechanism by which bergenin provides treatment of asthma, we used myeloid-specific SIRT1 conditional knockout mice to study the effect of bergenin in asthma models." (PMID 36313381, 2022). "Our study suggests that bergenin can improve asthma-induced airway inflammation and remodeling by activating SIRT1 in macrophages." (PMID 36313381, 2022). "In contrast, other studies have come to a contradictory conclusion that SIRT1 plays a role in promoting airway inflammation in asthma." (PMID 36117172, 2022). "Pts can relieve asthma by suppressing oxidative stress through the AMPK/Sirt1 and Nrf2/HO‐1 signaling pathways." (PMID 34342160, 2021). "In this study, our results reveal that Pts can relieve asthma by suppressing oxidative stress through AMPK/Sirt1 and Nrf2/HO‐1 pathways." (PMID 34342160, 2021). "Sirt1 is continuously activated in asthma, and inhibition of the Sirt1 pathway alleviates ovalbumin (OVA)‐induced asthma." (PMID 34342160, 2021). "In asthma patients, serum SIRT1 levels are positively correlated with IgE levels, and anti-SIRT1 autoantibodies are more abundant in inflammatory diseases such as psoriatic arthritis." (PMID 34946805, 2021). "The adenosine 5'‐monophosphate‐activated protein kinase (AMPK)/Sirtuin 1 (Sirt1) and nuclear factor‐E2‐related factor 2 (Nrf2)/Heme oxygenase‐1 (HO‐1) pathways relate closely with development of asthma." (PMID 34342160, 2021). "SIRT1 levels decrease in Th2 and non-Th2-related airway inflammation, indicating the role of SIRT1 in several endotypes and phenotypes of asthma." (PMID 32823491, 2020). "When we initially designed the current study, our main focus was the measurement of SIRT1, since we expected to have either increased or decreased levels in severe asthma." (PMID 32050426, 2020). "A number of studies have reported that the activity and expression level of SIRT1 are decreased in patients with asthma." (PMID 32050426, 2020). "We reviewed the cellular interactions between SIRT1 and inflammatory cells involved in virus-induced asthma exacerbations." (PMID 32823491, 2020). "Based on these previous reports, we will discuss about the impact of SIRT1 on virus-induced asthma exacerbations below." (PMID 32823491, 2020). "SIRT1 is a key regulator of GATA3 via its deacetylation, and in T-lymphocytes from patients with severe asthma, a decrease in SIRT1 has been linked to increased expression of IL-4 via increased GATA3 activation." (PMID 32823491, 2020). "In a clinical study, protein expression of SIRT1 activity obtained in peripheral blood cells from patients with severe asthma was decreased." (PMID 32050426, 2020). "The pan-HDAC inhibitor, Trichostatin-A, has similarly shown efficacy in asthma models, as has the allosteric activator of SIRT1, SRT1720." (PMID 30782202, 2019). "Although there are contrasting reports of the offensive and protective roles of Sirt1 in mouse asthma models, our results support the anti-allergic function of Sirt1." (PMID 28744004, 2017). "Current investigations have indicated that targeting SIRT1 could offer a promising new approach for asthma treatment." (PMID 41008562, 2025).
asthma (continued). "Besides SIRT1, other sirtuins including SIRT2, SIRT3, SIRT6, and SIRT7 have also been linked with asthma." (PMID 41008562, 2025). "SIRT1 has a pivotal role in mitigating inflammation in airway diseases such as asthma." (PMID 41008562, 2025). "While direct evidence showing an association between SIRT1 and glucocorticoid resistance in asthma is still lacking, studies have demonstrated that SIRT1 plays a critical role in suppressing allergic airway inflammation in vivo and in vitro." (PMID 40416964, 2025). "Additionally, SIRT1 influences pulmonary function in asthma patients through its effect on IL-6 levels via the Akt signaling pathway." (PMID 41008562, 2025). "However, the specific internal mechanism of hsa‐miR‐155‐5p and SIRT1 pathway during acute asthma exacerbation still needs in‐depth study." (PMID 38938285, 2024). "SIRT1 modulation by activation is an attractive asthma therapeutic strategy." (PMID 37987301, 2023). "Additionally, SIRT1 expression levels and activity have been found to be decreased in asthma and COPD patients." (PMID 37047327, 2023). "The disparity in the results is due to the controversial role of SIRT1 in asthma." (PMID 37987301, 2023). "Most studies suggest that SIRT1 plays a protective role in asthma." (PMID 36117172, 2022). "They found that the mRNA level of SIRT1 decreased in patients with asthma." (PMID 36117172, 2022). "Sirtuin 1 (SIRT1) reduces airway inflammation by affecting macrophages in asthma." (PMID 36313381, 2022). "Moreover, administration of EX-527, a specific SIRT1 inhibitor, alleviated airway inflammation in an OVA-induced mouse model of asthma via suppressing autophagy, which also suggests the pro-inflammatory role of SIRT1." (PMID 36117172, 2022). "Whether SIRT1 mediates the M2-type AM polarization and involves in the pathogenesis of asthma remain to be further elucidated." (PMID 34099590, 2021). "The AMPK/Sirt1 and Nrf2/HO‐1 pathways are potential targets for asthma treatement." (PMID 34342160, 2021). "Our study demonstrated that SIRT1 suppresses the allergic airway inflammation in macrophages, and suggested that activation of SIRT1 in macrophages may represent therapeutic strategy for asthma." (PMID 34099590, 2021). "Our study suggested that activation of SIRT1 in macrophages may represent therapeutic strategy for asthma." (PMID 34099590, 2021). "The effect of myeloid-specific SIRT1 deletion (Sirt1fl/fl-LysMcre) on airway inflammation was assessed by using in vivo models of asthma following allergen exposure and in vitro culture of primary bone marrow–derived macrophages (BMDMs) exposed to house dust mite (HDM)." (PMID 34099590, 2021). "An SIRT1-targeted treatment strategy may be effective in patients with virus-induced asthma exacerbation, who respond inadequately to existing therapies." (PMID 32823491, 2020). "Activation of SIRT1 suppresses epithelial damage, which may inhibit apoptosis and control viral-induced asthma exacerbations." (PMID 32823491, 2020). "In this review, we discuss the function of SIRT1 in inflammatory cells that play a role in virus-induced asthma exacerbations and examine the possibility of using SIRT1 as a target for treating virus-induced asthma exacerbations in the future." (PMID 32823491, 2020). "SIRT1 regulated IL-6 expression in the ovalbumin-induced asthma mouse model." (PMID 32823491, 2020). "The development of therapies targeting SIRT1 could be a boon for patients with virus-induced asthma." (PMID 32823491, 2020). "By applying the proven relationship between SIRT1 and IL-17 in these other diseases to viral-induced asthma, SIRT1 could become a new therapeutic target in the future." (PMID 32823491, 2020). "A better understanding of the SIRT1 mechanism may aid in the prevention and treatment of virus-induced asthma exacerbations." (PMID 32823491, 2020). "Collectively, with further research, therapies targeting SIRT1 may control asthma exacerbations through acetylation of the viral protein." (PMID 32823491, 2020).
asthma (continued). "Moreover, SIRT1 upregulators have protective anti-inflammatory and alleviating roles in asthma." (PMID 37987301, 2023). "Therefore, we speculate that bergenin can potentially contribute to the treatment of asthma by activating SIRT1." (PMID 36313381, 2022). "Hence, an increase in SIRT1 activity or protein expression in the lung may have beneficial effects against inflammation and circadian disruption in the pathogenesis of asthma." (PMID 36117172, 2022). "To further validate the role of ERK/p38 MAPK pathway in SIRT1 mediated- airway inflammation in asthma, we used the p38 inhibitor SB203580 and the ERK inhibitor U0126 to examine whether blocking ERK/p38 MAPK activation could reverse the amplified cytokine production caused by SIRT1 deficiency." (PMID 34099590, 2021). "However, the relationship between Pts and AMPK/Sirt1 and Nrf2/HO‐1 pathways in asthma is unclear." (PMID 34342160, 2021). "Therefore, the AMPK/Sirt1 and Nrf2/HO‐1 pathways may became potential targets for inflammatory diseases, including asthma." (PMID 34342160, 2021). "Thus, the epigenetic role of SIRT1 in macrophages of asthma also needs to be further investigated." (PMID 34099590, 2021). "However, the roles of SIRT1 in regulating macrophage activation in the pathogenesis of asthma remain unclear." (PMID 34099590, 2021). "Therefore, targeting SIRT1 is a novel strategy that may be effective for treating virus-induced asthma exacerbations in the future." (PMID 32823491, 2020). "However SIRT1-related signaling pathways are closely related to airway inflammation in asthma." (PMID 32823491, 2020). "Our results showed that, during acute asthma exacerbation, hsa‐miR‐155‐5p in AEC‐Exos regulates the differentiation of CD4+ T cells into Th2 type inflammation through the SIRT1 pathway, which was mediated through enhanced expression of STAT6 and GATA3." (PMID 38938285, 2024). "In this study, 10 hub targets of RDN were identified for asthma treatment, and RACK1 and SIRT1 were shown to play important roles in asthma." (PMID 35399637, 2022). "Asthma regulates metabolism and energy consumption by activating AMPK/SIRT1/PGC1 α signaling pathway." (PMID 34342160, 2021). "The relationship between SIRT1 and TGF-β, which was identified in IPF, has potential applications in virus-induced asthma exacerbations, but the mechanisms of this relationship are still unclear." (PMID 32823491, 2020). "During acute asthma exacerbation after RSV infection, AEC‐Exos promote the enhanced Th2 inflammation by transporting increased hsa‐miR‐155‐5p, which was mediated partly through SIRT1‐mediated pathway." (PMID 38938285, 2024). "In summary, our study showed that during acute asthma exacerbation after RSV infection, AEC‐Exos promote the enhanced Th2 inflammation through transportation of increased hsa‐miR‐155‐5p, which was mediated partly through SIRT1‐mediated pathway." (PMID 38938285, 2024). "The roles of SIRT1 and FoxO1 and their interactions in different types of diseases such as tumor progression, toxoplasmosis, and asthma are not completely elucidated." (PMID 37987301, 2023). "Corticosteroids have been among the main modalities for the treatment of asthma, but possible reasons for their inefficacy in severe asthma are the failure to recruit HDAC2/SIRT1 and the presence of oxidatively/post-translationally modified HDAC2/SIRT1 in asthmatics." (PMID 37245015, 2023). "Administration of SRT1720, a SIRT1 activator, could suppress airway inflammation in ovalbumin (OVA)-induced mouse models of asthma." (PMID 36117172, 2022). "In conclusion, our study shows that bergenin regulates the NF-κB pathway and blocks p65 translocation into the nucleus by activating SIRT1, thereby reducing the release of proinflammatory factors (such as IL-1β, IL-5, IL-6, and MMP-9 by macrophages) to play a role in asthma treatment." (PMID 36313381, 2022). "In conclusion, the current study failed to recognize a role for both Endocan and Sirtuin 1 in terms of asthma severity." (PMID 32050426, 2020).
asthma (continued). "In another study, SIRT1 activator (SIRT1720) treatment decreased the eosinophil count and IL-5 and Il-13 levels, but not IL-4 levels in the bronchoalveolar fluid and lung tissue in the ovalbumin-induced asthma mouse model." (PMID 32823491, 2020). "In this study, we demonstrated that Sestrin 2 levels were higher in both sputum supernatant and cell pellet of patients with severe asthma compared to those with milder forms of the disease, whereas neither Endocan nor SIRT1 serum levels differed between patients with different asthma severity." (PMID 32050426, 2020). "While they reported that serum SIRT1 levels were increased in OVA-sensitized and challenged mice model, SIRT1 levels were decreased in lung tissue, and more IL-4, IL-5, and IL-13 in BALF were found in the ovalbumin-induced asthma mouse model compared to the controls." (PMID 32823491, 2020). "The difference in the role of SIRT1 in asthma between adults and children is not clear." (PMID 32823491, 2020). "These lines of evidence suggest that activation of SIRT1 may lead to suppression of neutrophilic inflammation, possibly through suppression of CXCL8 and may be an effective therapeutic strategy, especially for steroid-resistant virus-induced asthma exacerbations." (PMID 32823491, 2020). "Thus, SIRT1 activators, including resveratrol, may be effective in targeting CXCL8-induced neutrophilic airway inflammation in virus-induced and steroid-resistant asthma exacerbations." (PMID 32823491, 2020).